MAPKBP1 (mitogen-activated protein kinase binding protein 1)
Description:
Negative regulator of NOD2 function. It down-regulates NOD2-induced processes such as activation of NF-kappa-B signaling, IL8 secretion and antibacterial response. Involved in JNK signaling pathway (By similarity).
Synonyms: JNKBP-1; JNKBP1; KIAA0596; NPHP20
Tractability: PROTAC: ubiquitination databases record sites on it; its protein half-life has been measured.
Gene: Protein-coding gene on chromosome 15 (41,774,434 to 41,827,855, forward strand). Ensembl gene ENSG00000137802.
Subcellular location: Cytoplasm; Nucleus; Cytoplasm, cytoskeleton, spindle pole
Subcellular location (Human Protein Atlas): Nucleoli; Nucleoli rim; Nucleoplasm
Gene Ontology:
Molecular function: protein binding
Biological process: negative regulation of canonical NF-kappaB signal transduction; negative regulation of defense response to bacterium; negative regulation of interleukin-8 production; positive regulation of JNK cascade; regulation of intracellular signal transduction
Cellular component: cytoplasm; mitotic spindle pole; nucleolus; nucleoplasm; nucleus; spindle pole
Genetic constraint (gnomAD): Loss-of-function variants: 67 observed, 169.51 expected, observed/expected ratio (o/e) 0.4, 90% interval 0.32 to 0.48. The upper end of that interval is the gene's LOEUF score, 0.48, which puts it in group 2 of 6, group 1 being the genes least tolerant of losing a copy. Missense variants: 1,565 observed, 1,956.1 expected, observed/expected ratio (o/e) 0.8, 90% interval 0.77 to 0.83. Synonymous variants: 697 observed, 763.4 expected, observed/expected ratio (o/e) 0.91, 90% interval 0.86 to 0.97.
Gene-disease validity (ClinGen):
ClinGen rates the evidence that MAPKBP1 causes each of these diseases.
nephronophthisis 20 (autosomal recessive): Definitive.
Homologues: Orthologues: chimpanzee MAPKBP1 (99% identical), macaque MAPKBP1 (97% identical), pig MAPKBP1 (90% identical), guinea pig MAPKBP1 (88% identical), rat Mapkbp1 (87% identical), mouse Mapkbp1 (86% identical), dog MAPKBP1 (77% identical), rabbit MAPKBP1 (77% identical), tropical clawed frog MAPKBP1 (61% identical). Paralogues in human: WDR62 (40% identical), TEP1 (12% identical), WDR7 (11% identical), WDR81 (10% identical), NEDD1 (8% identical), AHI1 (8% identical), NWD1 (8% identical), WDR17 (8% identical), WDR75 (8% identical), WDR27 (7% identical), PAFAH1B1 (6% identical), DAW1 (6% identical), and 14 more.
Diseases named in the same sentence as MAPKBP1 in open-access papers:
MAPKBP1 is named in the same sentence as 17 diseases in open-access papers, as found by Europe PMC text mining. Sharing a sentence is not in itself a finding about the gene and the disease. The quoted sentences say what the papers report.
chronic kidney disease (1 paper, 2025). Impairment of the renal function secondary to chronic kidney damage persisting for three or more months. "In our clinical end point analysis of chronic kidney disease progression, KF in MAPKBP1-associated disease showed a later onset—on average, about 10 years later—compared with all other forms of NPH." (PMID 40814602, 2025).
Chronic tubulointerstitial nephritis (1 paper, 2025). Chronic inflammation of the kidney affecting the interstitium of the kidneys surrounding the tubules. "Thus, MAPKBP1 defects induce basal body conditions that are comparable to continuous JNK activation, which is in line with the inflammatory fibrosis observed in chronic tubulointerstitial nephritis of NPH." (PMID 40814602, 2025).
dependent (1 paper, 2025). "With this study, we provide strong evidence for a reclassification of MAPKBP1-associated kidney disease into the spectrum of cilia-dependent NPH clinically characterized by a milder natural course." (PMID 40814602, 2025).
epilepsy (1 paper, 2015). A brain disorder characterized by episodes of abnormally increased neuronal discharge resulting in transient episodes of sensory or motor neurological dysfunction, or psychic dysfunction. "Our results showed that IRAK1 (P = 1.04 × 10−7), the targets of miR-146a, MAPKBP1 (P = 10.44 × 10−7) and CASP6 (P = 0.001), targets of miR-106b, were down-regulated, whereas MAP2K6 (P = 5.30 × 10−5), target of miR-194-5p, was up-regulated in epilepsy patients compared with normal controls." (PMID 25825351, 2015).
nephronophthisis (1 paper, 2018). Progressive tubulointerstitial injury, inherited in an autosomal recessive pattern, caused by mutations in genes involved in ciliary function, which may result in an end stage renal failure. "Interestingly, depletion of the latest gene product identified to cause nephronophthisis (MAPKBP1) leads to increased DNA-damage response signaling, but MAPKBP1 has not been detected in the cilium or its appendages." (PMID 30111592, 2018).
Onset (1 paper, 2025). The age group in which disease manifestations appear. "In contrast to NPHP1-associated kidney disease, which may similarly account for adult-onset KF (PMID: 29654215), retinal impairment was not part of the phenotypic spectrum in any of the published cases with MAPKBP1 deficiency." (PMID 40814602, 2025).
kidney disease (1 paper, 2025). "Combined clinical end point analysis in all patients with MAPKBP1-associated kidney disease revealed a median age of 23 years and a mean age of 20.4 ± 1.8 years at KF." (PMID 40814602, 2025). "We demonstrated that MAPKBP1-NPH follows a distinct natural history, characterized by predominantly nonsyndromic kidney disease and exceptionally slow progression." (PMID 40814602, 2025).
MAPKBP1 also shares sentences with these, for which no sentence is quoted: ciliopathies (2 papers); tumor (2); acute myeloid leukemia (1); breast carcinoma (1); cancer (1); cystic kidney disease (1); Insulin resistance (1); Joubert syndrome (1); Obesity (1); virus infection (1).